TMEM237 (transmembrane protein 237)
Description:
Component of the transition zone in primary cilia. Required for ciliogenesis.
Synonyms: ALS2CR4; JBTS14
Tractability: Antibody: its Gene Ontology location is reachable by antibodies, with high confidence; UniProt predicts a signal peptide or a membrane-spanning region. PROTAC: ubiquitination databases record sites on it; its protein half-life has been measured.
Gene: Protein-coding gene on chromosome 2 (201,620,184 to 201,643,570, reverse strand). Ensembl gene ENSG00000155755.
Subcellular location: Membrane; Cell projection, cilium
Subcellular location (Human Protein Atlas): Microtubules; Nuclear speckles; Plasma membrane; Primary cilium; Cytokinetic bridge; Primary cilium transition zone
Gene Ontology:
Molecular function: protein binding
Biological process: cilium assembly; regulation of Wnt signaling pathway; protein localization to ciliary transition zone
Cellular component: ciliary transition zone; cilium; membrane; MKS complex
Genetic constraint (gnomAD): Loss-of-function variants: 41 observed, 40.36 expected, observed/expected ratio (o/e) 1.02, 90% interval 0.79 to 1.32. The upper end of that interval is the gene's LOEUF score, 1.32, which puts it in group 5 of 6, group 1 being the genes least tolerant of losing a copy. Missense variants: 384 observed, 377.55 expected, observed/expected ratio (o/e) 1.02, 90% interval 0.94 to 1.11. Synonymous variants: 115 observed, 135.91 expected, observed/expected ratio (o/e) 0.85, 90% interval 0.73 to 0.99.
Gene-disease validity (ClinGen):
ClinGen rates the evidence that TMEM237 causes each of these diseases.
Joubert syndrome 14 (autosomal recessive): Definitive. Any Joubert syndrome in which the cause of the disease is a mutation in the TMEM237 gene.
Homologues: Orthologues: chimpanzee TMEM237 (99% identical), macaque TMEM237 (94% identical), dog TMEM237 (87% identical), pig TMEM237 (86% identical), mouse Tmem237 (82% identical), rabbit TMEM237 (80% identical), rat Tmem237 (80% identical), guinea pig TMEM237 (78% identical), tropical clawed frog tmem237 (58% identical), zebrafish tmem237b (52% identical), zebrafish tmem237a (49% identical).
Diseases named in the same sentence as TMEM237 in open-access papers:
TMEM237 is named in the same sentence as 13 diseases in open-access papers, as found by Europe PMC text mining. Sharing a sentence is not in itself a finding about the gene and the disease. The quoted sentences say what the papers report.
ciliopathy (5 papers, 2013 to 2025). A genetic disorder of the cellular cilia or the cilia anchoring structures, the basal bodies, or of ciliary function. "The TMEM237 promoter cg23849778 methylation correlated with ADCOMS scores, and TMEM237 variants are associated with ciliopathy and neurodevelopmental delays." (PMID 40386807, 2025). "The discovery that TMEM237 (transmembrane protein 237 or JBTS14, Joubert syndrome 14) harbored causative mutations in ciliopathy patients provides such an example." (PMID 25780610, 2014). "Furthermore, TMEM-218 can be positioned genetically and hierarchically within the MKS module, likely as a peripheral component, similar to MKS-3 (Tmem67), JBTS-14 (Tmem237), and MKS-6 (Cc2d2a), which are all ciliopathy-associated." (PMID 26982032, 2016).
Joubert syndrome (2 papers, 2014 to 2019). Joubert syndrome (JS) is characterized by congenital malformation of the brainstem and agenesis or hypoplasia of the cerebellar vermis leading to an abnormal respiratory pattern, nystagmus, hypotonia, ataxia, and delay in achieving motor milestones. "This male patient has been suspected to be affected with Joubert syndrome which is known to be linked to biallelic TMEM237 variants, and had defective vision and global developmental delay." (PMID 31238879, 2019).
Joubert syndrome types 3 (1 paper, 2024). "We identified two frameshift variants in the AHI1 and TMEM237 genes, leading to Joubert syndrome types 3 and 14, respectively." (PMID 38570878, 2024).
Meckel-Gruber syndrome (1 paper, 2016). "However, we also observed a trend where genes that cluster in the same ciliary compartment tended to cause a similar phenotype; e.g., mutations in the transition zone genes CC2D2A, TCTN2, TMEM237, and CEP290 almost always resulted in either Joubert or Meckel-Gruber syndrome phenotypes." (PMID 27894351, 2016).
microcephaly (1 paper, 2021). A congenital or acquired developmental disorder in which the circumference of the head is smaller than normal for the person's age and sex. "Although in this study we excluded primary microcephaly and dysmorphies and obvious syndromes from the beginning, we found 4 syndromes, three of which were Joubert spectrum syndrome (No. 21, 25, and 27) due to pathogenic variants in TMEM237, LAMA, and KIAA0586, respectively." (PMID 34540776, 2021).
TMEM237 also shares sentences with these, for which no sentence is quoted: Joubert syndrome and related disorders (2 papers); amyotrophic lateral sclerosis (1); developmental delay (1); kidney disease (1); liver fibrosis (1); Neurodevelopmental delay (1); orofaciodigital syndrome (1); retinal diseases (1).